MUC1 (mucin 1, cell surface associated)
Diseases named in the same sentence as MUC1 in open-access papers (continued):
Sharing a sentence is not in itself a finding about the gene and the disease.
breast carcinoma (continued). "Diagnostic and prognostic use of differentially expressed MUC1 variants has been reported for ovarian and breast cancers." (PMID 19578514, 2008). "In another report, we pointed out that low MUC1 serum levels in stage I breast cancer patients were associated with the presence of free and complexed anti-MUC1 antibodies." (PMID 17064405, 2006). "The association of MUC1 overexpression with loss of cell polarity has been observed in breast carcinomas." (PMID 17078870, 2006). "Overall, these data indicate that endogenous GATA3 protein molecules from the MCF7 breast cancer cell line were able to associate with the putative GATA3-binding site of MUC1 promoter sequence, as demonstrated with in vivo and in vitro assays." (PMID 17078870, 2006). "Besides MUC16, other members of the mucin family, including MUC19 and MUC1 have been implicated in the glucose metabolism of different cancers, including breast cancer, bladder cancer, and endometrial carcinoma." (PMID 39219440, 2024). "MUC1 interacts with EGFRs to activate cell proliferation-related signaling cascades, and it has been implicated in the invasion and metastasis of different types of tumors including breast cancer." (PMID 38543147, 2024). "Moreover, there have been interesting reports about the association of MUC1 sialylation with a better prognosis in breast cancer as a result of inhibiting MUC1-galectin-3 interaction." (PMID 37345016, 2023). "Experimental studies have suggested that MUC1 functions as an oncoprotein and plays an important role in multiple steps of carcinogenesis including tumor proliferation, metabolism, invasion, and metastasis, and MUC1 overexpression was associated with poor outcomes in lung cancer and breast cancers." (PMID 36831343, 2023). "Likewise, a synthetic MUC1 glycopeptide linked to a B-cell and a T-cell epitope together with poly I:C as an adjuvant elicited significant IgG titers against tumor-associated MUC1 expressed in breast cancer cells." (PMID 36291752, 2022). "Furthermore, sialylated T-antigen was associated with an enhanced growth rate of mammary carcinoma cells in MUC1 transgenic mice and with the malignancy of bladder cancer, ovarian cancer, and colorectal cancer in humans." (PMID 35743163, 2022). "The MUC-1 is generally expressed at low levels by normal simple secretory epithelial tissues, its overexpression is often associated with most carcinomas and in particular by breast cancers, and correlates with high metastatic and poor survival." (PMID 34001936, 2021). "The transcriptional profile of these MUC1-ST-induced macrophages reveals a phenotype with multiple upregulated factors associated with poor prognosis, and defines a signature associated with poor survival of breast cancer patients." (PMID 33149188, 2020). "Thus, the tumor-associated carbohydrate antigen (TACA) present in breast cancer was associated with MUC1." (PMID 32075174, 2020). "Furthermore, autoantibodies against aberrantly glycosylated MUC1 in early‐stage breast cancer are associated with a better prognosis." (PMID 33084221, 2020). "We also found that the expression of the MUC1 gene, which is overexpressed in breast cancer patients, and encodes the widely used CA 15‐3 (Cancer antigen 15‐3) serum biomarker for breast cancer, was significantly reduced upon SAM + 5AzadC combination treatment." (PMID 32720467, 2020). "The fact that MUC1 overexpression was observed in various places, including primary sites, metastatic lymph nodes, migrating tumor cells, and secondary sites, indicated a higher risk of metastasis as well as poor prognosis of mammary tumors with the high level of MUC1 expression." (PMID 33375426, 2020). "In breast cancer, overexpression of MUC1 is associated with poor prognosis, suggesting that Siglec-9 may play an important role in the progression of breast cancer." (PMID 31430935, 2019).
breast carcinoma (continued). "In conclusion, the mAb GGSK-1/30 represents a platform, which can be used (i) as a diagnostic tool for the detection of hu(TA)MUC1 in early breast cancer diagnosis, (ii) as a prognostic biomarker, (iii) as a companion diagnostic during therapy and (iv) in future perspective in radioimmunotherapy." (PMID 31588183, 2019). "Tumor-associated MUC1 is expressed on over 90 % of all breast cancer entities and differs strongly from its physiological form on epithelial cells, therefore presenting a unique target for breast cancer diagnosis and antibody-mediated immune therapy." (PMID 31588183, 2019). "Mucin 1 (MUC1), a glycoprotein which lines the surface of epithelial cells, has been used as a target for aptamer-based capture strategies, since the overexpression of MUC1 is associated with several cancers, including breast cancer." (PMID 29751641, 2018). "Moreover, loss of core 1 O-glycans in spontaneous mammary cancer models delayed the onset and growth of the tumours and impaired the localisation of Muc1." (PMID 29903935, 2018). "Also in our lab, we have demonstrated diagnostic potential of TPI, MNSOD, PGAM1, MUC1 & CMYC autoantibodies in canine mammary tumours by ELISA." (PMID 30361548, 2018). "MUC1 overexpression was associated with a recurrence and distance metastasis in breast cancer." (PMID 28817726, 2017). "Further, overexpression of MUC1 is strongly associated with chemoresistance in breast cancer." (PMID 28464016, 2017). "They postulated that an understanding of the epigenetic changes of MUC1 may be of importance for prediction of risk and outcome for patients diagnosed with breast cancer." (PMID 28241424, 2017). "In addition to these short cancer-associated antigens, MUC1 expressed by breast carcinoma cells also carries the mono- and disialyl core 1 structure (ST, NeuAcα2-3Galβ1–3[NeuAcα2–6]+/–GalNAcα1-O-Ser/Thr) found widely in normal cells." (PMID 28414807, 2017). "In breast cancer, however, mutations in the MUC1 gene may only present as somatic changes within tumour DNA, and are unlikely to be clinically useful in prediction of familial risk." (PMID 28241424, 2017). "In summary, our results indicate that instead of SRC population and types, the expression level of MUC1 and/or the presence of cytoplasmic staining with circumferential membranous accentuation pattern in breast cancers showed significant association with adverse clinicopathological parameters." (PMID 27846863, 2016). "Pt12 and anti-MUC1 caused the reduction of MMP in 57 % of breast cancer cells." (PMID 26112902, 2015). "We thus hypothesize that breast cancer cells displaying mem-PankoMab-GEXTM positivity are predisposed to be recognized by endogenous or newly induced anti-MUC1 auto-antibodies potentially acting via ADCC mechanisms, as demonstrated for PankoMab-GEXTM." (PMID 25986064, 2015). "In vitro studies demonstrated that the expression of MUC1 is involved in the invasion and resistance to genotoxic anticancer reagents suggesting that it is closely associated with poor prognosis of patients with breast cancer." (PMID 24639126, 2014). "MUC1 gene encodes a highly glycosylated protein located on the apical surface of mammary epithelia that is aberrantly overexpressed in approximately 90% of human breast cancers." (PMID 24073403, 2013). "Furthermore, identified six genes (TSPYL5, CD55, CCNE2, DCK, BBC3, and MUC1) susceptible to breast cancer were verified through the literature mining, GO analysis, and pathway functional enrichment analysis." (PMID 24073403, 2013). "To date, several tumor-specific carbohydrates were increased by different degrees and have been found be associated with breast cancer and have been used in tumor therapy as targeted antigens, such as Tn antigen, sialyl Lewis X antigen, MUC1 glycoprotein, Her-2/Neu glycoprotein and CEA." (PMID 24009699, 2013). "Likewise, MUC1 is frequently overexpressed and associated with a poorer prognosis in many cancers including breast cancer." (PMID 23300877, 2012).
breast carcinoma (continued). "MUC1 expression enhances tumor cell invasion, proliferation and survival and is thereby linked to metastasis in several epithelial cancers, including pancreatic and breast carcinomas." (PMID 22586492, 2012). "We found that constitutive MUC1 levels are significantly associated with stable differences in intrinsic Δψm of subcloned cell lines derived from colonic and mammary carcinoma cell populations, with higher levels of MUC1 exhibited in cells with elevated intrinsic Δψm." (PMID 21966455, 2011). "Pregnancy and lactation induce an immunologic response against MUC1 that could play a role in the mechanisms involved in the association between multiparity and a lower risk of breast cancer." (PMID 24212946, 2011). "However, the association between aberrant MUC1 expression pattern and phenotypic differentiation of breast carcinomas is still unclear." (PMID 20550696, 2010). "AAbs to MUC1 have been described and correlated with a more favorable prognosis; thus, it seems that risk for breast carcinoma might be reduced by preexisting MUC1-specific immunity." (PMID 21113302, 2010). "Obviously, serum AAb-assay against MUC1 protein only is of little value for screening and early diagnosis of breast carcinoma; however, AAbs to MUC1 may have promising diagnostic potential when incorporated in AAb assays against a panel of TAAs." (PMID 21113302, 2010). "However, while attempting to develop a DC immunotherapy protocol for the treatment of breast cancer based on the tumour-associated MUC1 glycoforms, we found that unpulsed DCs can affect tumour growth." (PMID 18253127, 2008). "The mucin profile has other potential therapeutic ramifications; in many breast cancers, the glycosylation of the MUC-1 mucin side chains is altered and the mucin variant presents a potential target for immunotherapy; however, this is not an option for mucinous carcinomas which do not produce MUC-1." (PMID 15700031, 2005). "further revealed that MUC1-ST binding to Siglec-9 promotes differentiation of monocytes into tumor-associated macrophages (TAMs), which recruit neutrophils, inhibit T cell function, and promote tumor cell invasion, closely associated with poor prognosis in breast cancer patients." (PMID 38361923, 2024). "Furthermore, MUC1 overexpression has also been linked to chemo-resistance in breast cancer." (PMID 36405816, 2023). "Therefore, we wondered whether loss of MUC1 could enhance the sensitivity to apigenin in breast cancer cells." (PMID 35970845, 2022). "Thus, SMAD2 may play a key role in regulating Tn antigen expression in proteins such as MUC-1 that are associated with breast cancer progression." (PMID 34367349, 2021). "MUC1 expression is increased in many epithelial cancers, which is associated with a high metastatic potential and poor prognosis whereas the presence of sialylated MUC1 glycoform was shown to be associated with a better prognosis in patients with breast cancer." (PMID 32280709, 2020). "Several studies including ours have also demonstrated that BCG could be engineered to express mucin-1 (MUC1), a candidade tumor-associated antigen for breast cancer and other epithelial adenocarcinomas, in a manner of multiple tandem repeats with coexpression of IL-2, GM-CSF, or CD80." (PMID 21941579, 2011). "The authors concluded that measurement of serum AAbs to MUC1 protein only is of little value for screening and early diagnosis of breast carcinoma; however, AAbs to MUC1 may have promising diagnostic potential when incorporated in AAb assays against a panel of TAAs." (PMID 21113302, 2010). "Moreover, there is support for the notion that preexisting AAbs to MUC1 may reduce the risk of developing breast carcinoma and presence of AAbs to MUC1 in breast carcinoma is correlated with a more favorable prognosis." (PMID 21113302, 2010). "In this investigation, we examined the effect of TA-MUC1 on the cholesterol and fatty acid metabolism of cancer cells via MUC1 gene knock down breast cancer cells." (PMID 41516394, 2026).
breast carcinoma (continued). "Our previous research showed that a significant reduction in PAR1 and PAR4 coincides with reduced p-Akt, tissue factor (TF) and thrombin activity in MUC1 gene knock down breast cancer cells." (PMID 41516394, 2026). "This demonstrated that cholesterol metabolism and regulation were modulated by the MUC1 gene in breast cancer cells." (PMID 41516394, 2026). "CEA is a protein frequently overexpressed in a variety of cancers, including breast, colon, and pancreatic cancers, while MUC1 is a glycoprotein often aberrantly expressed in breast cancer." (PMID 40333213, 2025). "The transmembrane terminal subunit of MUC-1 (MUC-1-C) functions as an oncoprotein, and its gene amplification is linked to 40% of breast cancers." (PMID 41463161, 2025). "Many cellular glycoproteins bind with Gal-2, such as ganglioside GM1 in neuroblastoma cells, mucin protein MUC1 in colon and breast cancer, and glycoprotein MUC5AC in gastric mucus." (PMID 40134029, 2025). "Another peptide-based vaccine being explored for breast cancer targets the transmembrane glycoprotein MUC1." (PMID 40333213, 2025). "Clinical validation experiments successfully differentiated plasma samples from breast cancer patients and healthy donors based on exosomal MUC1 expression profiles." (PMID 40422035, 2025). "Clinically, sialic acid-rich glycoconjugates serve as established biomarkers (CA19-9/SLex in pancreatic cancer; CA125/MUC16 in ovarian cancer; CA15-3/MUC1 in breast cancer), while specific sialyltransferases show prognostic potential." (PMID 41154604, 2025). "Emerging targets include MUC1 (Mucin 1), particularly its cleaved isoform MUC1*, which functions as a growth factor receptor and is overexpressed in >80% of breast carcinomas." (PMID 41348261, 2025). "In the realm of solid tumors, laboratory investigations have explored various tandem CAR combinations, such as HER2/IL13Ra2 for glioblastoma treatment and HER2/MUC1 for breast cancer therapy." (PMID 40382583, 2025). "MUC-1 in breast cancer cells is hypo-glycosylated, apically localized, and aberrantly expressed on more than 90% of the breast cancer cell membranes." (PMID 41463161, 2025). "CA15-3, a soluble fragment of MUC1 typically used as a serum biomarker for breast cancer, displays substantial amounts of TACAs such as sialyl-Lewis antigens, sialyl-Tn, Tn, sialyl-T, and T." (PMID 41150750, 2025). "CA27-29, an epitope of the MUC1 glycoprotein, is another valuable marker as elevated levels indicate breast cancer recurrence or metastasis, demonstrating higher sensitivity and specificity, especially in advanced or recurrent disease." (PMID 41301860, 2025). "An adenovirus serotype 5 vector was engineered to incorporate a tumor-selective MUC1 promoter and a firefly luciferase reporter gene, acting as a targeted delivery vehicle for transporting genetic sequences into breast cancer cells." (PMID 41375132, 2025). "Mucin 1 (MUC1) is a heterodimeric protein that is aberrantly overexpressed in most human breast cancers." (PMID 40708788, 2025). "Breast cancer: Twelve patients received PD-1 KO anti-MUC1 CAR T cells for MUC1-positive advanced breast cancer." (PMID 41354926, 2025). "For example, MUC1 aptamer targets the MUC1 glycoprotein, which is overexpressed on breast cancer cells." (PMID 40688030, 2025). "The MUC1 gene is regulated by DNA methylation in some breast cancer cell lines based on the results of Sanger sequencing." (PMID 41187747, 2025). "In these cases, the researchers first identified several overexpressed proteins in cancer, including HER2 in breast cancer and MUC1 and CEA in pancreatic cancer." (PMID 40507272, 2025). "Among the various N-acetylglucosaminyltransferases (GalNAcTs), GalNAcT6 has been identified to stabilize MUC1, and GalNAcT14 is highly expressed in breast cancers." (PMID 40699805, 2025).
breast carcinoma (continued). "The ABCSF 34 trial in breast cancer vaccine development studied a MUC1-based vaccine, tecemotide, that in combination with neoadjuvant systemic therapy for early breast cancer significantly improved recurrence-free and overall survival." (PMID 41295524, 2025). "We investigated the expression of MUC1 protein in human breast cancer tissues using immunostaining with an anti-hMUC1 monoclonal antibody and compared it with MUC1 expression in normal breast tissues." (PMID 41471303, 2025). "With the extensive involvement of MUC1 in breast cancer, recent studies have focused on the role of mucin in immunotherapy, which will be further discussed in a later chapter." (PMID 40699805, 2025). "Upon entering breast cancer cells, the MUC1 promoter was activated, initiating the expression of the reporter gene and resulting in the emission of a detectable luminescent signal that can be monitored externally for tumor detection." (PMID 41375132, 2025). "In studies of breast cancer cells, the increased activity in sialyltransferase (STGal-I) was observed in the exposure of otherwise cryptic peptide epitopes expressed by MUC1." (PMID 40699805, 2025). "In studies of mammary tumors, MUC1 augments the dimerization of Her 2 and EGFR, which has been associated with invasive papillary mucinous neoplasm." (PMID 40699805, 2025). "The MTT assay showed that the anti-MUC1 conjugated by nanochitosan was more effective than the free anti-MUC1 nanobody in inhibiting breast cancer cell (MCF-7) growth." (PMID 38341580, 2024). "For example, breast cancer frequently harbors aberrantly glycosylated mucin 1 (MUC1) at upregulated expression levels." (PMID 38731892, 2024). "During tumorigenesis and progression, significant changes occur in the expression and function of MUC1, with over 90% of breast cancer cases exhibiting its abnormal overexpression." (PMID 38361923, 2024). "For example, while MUC1 is overall highly expressed in most breast cancer models, some cell lines like the triple-negative MDA-MB-231 are deficient." (PMID 38675909, 2024). "CA 15-3, also known as Mucin-1 (MUC-1), is a 300 kDa carbohydrate antigen found in normal breast and breast cancer cells." (PMID 38966130, 2024). "MUC1 also enhances the invasiveness of breast cancer cells by disrupting ATAD3A and activating Pink1-related mitochondrial autophagy, revealing the critical role of the MUC1/ATAD3A/Pink1 axis in breast cancer progression." (PMID 38361923, 2024). "When comparing different molecular biological subtypes of breast cancer, it was shown that a decrease in the level of MUC1 CA 15-3, CA 27.29, and MCA was observed only for HER2-positive subtypes (luminal B (HER2+) and non-luminal)." (PMID 39456554, 2024). "Given that MCF-7 cells are a well-established model in breast cancer research and demonstrated high MUC1 expression in our experiments, we selected MCF-7 cells for the generation of the CTC model samples." (PMID 39886667, 2024). "The role of MUC1 in breast cancer immunity research, particularly in modulating tumor immune escape mechanisms, has garnered significant attention." (PMID 38361923, 2024). "The same authors later developed nanoparticles loaded with DTX and cMET siRNA to target MUC-1 overexpressing breast cancer cells, particularly SKBR3 cells." (PMID 38675202, 2024). "MUC-1 mucins, secreted by glandular epithelial cells and upregulated in breast cancer patients’ serum, particularly CA15-3, reflect the clinical course in metastatic cancer scenarios." (PMID 38542382, 2024). "The surface enhanced Raman scattering (SERS) is used for detection of the breast cancer biomarker MUC1, and the MUC1 specific aptamer is fabricated on core–shell (Au@Fe3O4) NPs to capture MUC1 molecules on the surface of tumor cells." (PMID 38733011, 2024). "Specifically, the evaluation of the proportion of CD63/EpCAM/MUC1-triplepositive EVs in breast cancer can be enhanced through the analysisof these EVs at an individual level." (PMID 39175406, 2024).